TLR4 (toll like receptor 4)
Diseases named in the same sentence as TLR4 in open-access papers (continued):
Sharing a sentence is not in itself a finding about the gene and the disease.
colon carcinoma (156 papers, 2008 to 2025). "The TLR4 rs1927914 polymorphism influence the susceptibility to colon cancer, with the G allele offering a protective effect through modulation of gene expression." (PMID 39026223, 2024). "Our study indicated that TLR4 rs1927914 polymorphism is associated a decreased colon cancer risk, consistent with findings in other cancers." (PMID 39026223, 2024). "Our results demonstrated that the G-allele of the TLR4 rs1927914 polymorphism is significantly associated with a decreased risk of colon cancer (OR = 0.68, 95%CI = 0.50–0.91)." (PMID 39026223, 2024). "The identification of the TLR4 rs1927914 polymorphism as a factor associated with decreased colon cancer risk provides valuable insights into the genetic underpinnings of this disease." (PMID 39026223, 2024). "The TLR4-D299G mutation promotes carcinogenesis in Caco-2 cells and correlates with advanced stages of colon cancer in humans." (PMID 38930793, 2024). "The presence of G-allele in TLR4 rs1927914 was associated with a decreased colon cancer risk (OR = 0.68, 95%CI = 0.50–0.91)." (PMID 39026223, 2024). "These insights enhance our understanding of the genetic determinants of colon cancer risk and highlight TLR4 as a promising target for cancer prevention strategies." (PMID 39026223, 2024). "The TLR4 rs1927914G allele containing genotype is associated with a reduced risk of colon cancer in males (OR = 0.58, 95%CI = 0.38–0.87) when stratified by gender." (PMID 39026223, 2024). "In colon cancer cells, the luciferase activity driven by the TLR4 promoter containing the rs1927914A allele was significantly higher compared to that driven by the promoter with the G allele." (PMID 39026223, 2024). "TLR4 has been implicated in both triggering innate immune response against bacteria and colon cancer development." (PMID 35468924, 2022). "In this regard, TLR4 has been demonstrated to enhance colon cancer, whereas TLR4 deficiency lessens the signs of inflammation and tumor load." (PMID 31480568, 2019). "Conversely, overexpressing TLR4 using the CD4-TLR4 transgene in the intestinal epithelium of APCMin/+ mice that are genetically susceptible to colon carcinoma reduced tumorigenesis by increasing apoptosis." (PMID 28531216, 2017). "The associations between TLR4 rs10759931 SNP and TLR4 expression in colon cancer tissues, TLR2-196 to TLR2-174del SNP, and TLR2 mRNA expression have been reported." (PMID 28912808, 2017). "Here, we used invasive Caco-2 cell-based colon carcinoma cells that harbor the gene variant TLR4-D299G." (PMID 27271572, 2016). "Our aim was to evaluate the association between the expression and the polymorphism of TLR4/NF-κB pathways and colon cancer." (PMID 26771524, 2016). "Adhesion and metastasis in human colon cancer has been linked to TLR4 activation as well as migration in glioblastoma." (PMID 27941651, 2016). "To evaluate the association between TLR4 SNPs with a younger age at diagnosis of colon cancer, we stratified the patients as ≤50 or >50 years of age." (PMID 26771524, 2016). "In agreement with Cammarota and Wang, we found that TLR4 protein expression in the stromal compartment was associated with more advanced stages of colon cancer." (PMID 24887394, 2014). "The present study evaluated the impact of two common single nucleotide polymorphisms (SNPs) of the human TLR4 gene on the chemosensitivity of colon cancer cells to 5-fluorouracil." (PMID 24250621, 2013). "It is also worth noting that colon cancer patients carrying the minor allele of TLR4-rs4986790 exhibited worse progression free survival and OS after treatment with chemotherapy." (PMID 21931695, 2011). "Functional assays demonstrated that in HCT116 and LOVO colon cancer cells, the luciferase activity driven by the TLR4 promoter with the rs1927914A allele was 5.43 and 2.07 times higher, respectively, compared to that driven by the promoter containing the rs1927914G allele." (PMID 39026223, 2024).
colon carcinoma (continued). "These insights suggest that the protective effect of the TLR4 rs1927914G allele in colon cancer may result from enhanced Oct-1 binding, leading to reduced TLR4 expression and decreased cancer risk." (PMID 39026223, 2024). "Overexpression of TLR4 has been associated with poor prognosis in breast and colon cancers." (PMID 36030212, 2022). "An in vitro study using SPA4 demonstrated a reduction in NF-κB-dependent cytokine production, migration, and invasion of the SW480 colonic cancer cell line suggesting that interfering with TLR4 signaling may be of benefit in colitis-associated cancer." (PMID 29515999, 2018). "In addition to IBD, TLR4 expression is increased in colitis-associated cancer and in some sporadic colon cancers." (PMID 26755160, 2016). "A TLR4 SNP (rs11536898) is also associated with colon cancer.Recently, a human TLR4 (Asp299Gly) SNP has been suggested to be more specifically associated with LPS hypo-responsiveness and an increased risk of developing prostate cancer among a North Indian population." (PMID 26771524, 2016). "In summary, we provide links between TLR4 gene expression and TLR4 polymorphisms, which have been hypothesized as important to the carcinogenic process of colon cancer in the Saudi Arabia population." (PMID 26771524, 2016). "Moreover, the same study has implicated TLR4 in promoting immune escape of the human colon cancer cells by inducing immunosuppressive factors and apoptosis resistance." (PMID 27092172, 2016). "Also, TLR-4 expression in colon cancer cells is associated with an increased risk of formation of liver metastasis in colon cancer patients and confers a worse prognosis." (PMID 23071493, 2012). "They showed that the exposure of TCS (80 ppm in diet) caused adverse effects on colonic inflammation and colon cancer, which was associated with reduced diversity of the gut microbiota and decreased abundance of beneficial gut bacteria such as Bifidobacterium as well as TLR4 signaling." (PMID 36401221, 2022). "Both TLR4 and its adapter MyD88 are increased in human sporadic colon cancer compared to surrounding normal and adenomatous epithelium, and are associated with poor patient prognosis, thereby implying a functional role for the LPS-TLR4-NF-κB pathway in colon cancer." (PMID 25978030, 2015). "Parabacteroides_distasonis attenuates toll-like receptor 4 signaling and Akt activation and blocks colon tumor formation in high-fat diet-fed azoxymethane-treated mice." (PMID 38658841, 2024). "Previous studies showed that colon cancer patients with low TLR4 expression exhibit extended survival times and the TLR4 signaling pathway holds a significant role in CRC pathogenesis." (PMID 38930793, 2024). "This underscores their potential as therapeutic targets for managing the TLR4-mediated EMT process in colon cancer cells via TAp63 regulation." (PMID 38930793, 2024). "Inhibiting TLR4 signaling significantly reduced colonic tumor development, accompanied by fewer infiltrating macrophages and lower pro-inflammatory cytokine levels." (PMID 38930793, 2024). "GSK-3βregulates cellular metabolism and EMT processes, with TLR4-triggered GSK-3β activation promoting colon cancer cell migration and invasion." (PMID 38930793, 2024). "Resistin was found to bind to TLR4 on the membrane of colon cancer cells and initiate TLR4-MyD88 dependent ERK activation, leading to cell arrest in the G1 phase." (PMID 38553715, 2024). "Colon cancer cells initiate epithelial-mesenchymal transition when TLR4-mediated galectin-1 synthesis is triggered by the formation of ADAM10 and ADAM17-associated lactate." (PMID 37936149, 2023). "The interaction of LY96 and TLR4 promotes the release of pro-inflammatory cytokines and adhesive molecules, which accelerates colon cancer growth and lung metastasis." (PMID 37662929, 2023).
colon carcinoma (continued). "Long-term UC patients have a great risk of developing colitis-associated cancer, and TLR4/NF-κB-, TNF-α-, and IL-6-related pathways are crucial in the progression of UC to colon cancer." (PMID 36310619, 2022). "Our results showed that depletion of Tlr4 decreased colon tumor numbers, volumes, and diameters compared with WT mice." (PMID 34914638, 2022). "LY96 interacted with TLR4 and activated the nuclear factor-κB (NF-κB) pathway, and thereby promoted the production of pro-inflammatory cytokines and adhesive molecules in colon cancer cells, which accelerate colon cancer growth and lung metastasis." (PMID 35647025, 2022). "Progressively activated TLR4 encourages the proliferation of colon cancer cells and extricates cancer cells from death." (PMID 35269806, 2022). "They observed that by inhibiting TLR4 with an antagonist during intestinal inflammation, the development and progression of colonic tumours was significantly reduced compared to control mice." (PMID 35962138, 2022). "By stimulation of the toll-like receptor 4 (TLR4) with bacterial lipopolysaccharide (LPS), colon cancer cells release galectin-1 which induced lactate production and EMT." (PMID 34356834, 2021). "Using an antagonist TLR4 antibody, the study team demonstrated that the inhibition of TLR4 markedly suppressed the development of colonic tumors in the WT mice." (PMID 34479599, 2021). "For example, in a mouse model of colon cancer, epithelial TLR4 activity induced the beta-catenin pathway, potentially linking TLR4 with oncogenesis." (PMID 35048056, 2021). "In our previous study on colon cancer cells, we demonstrated that LPS had a synergistic effect with 5-FU on up-regulation of TLR-4 expression on the surface of HCT116 cells (colon cancer cells)." (PMID 34904014, 2021). "The cancer genome atlas (TCGA) databases were selected to predict the differential expression of TLR4 in colon cancer and its correlation with MMR genes." (PMID 34026821, 2021). "CRX-526 was reported to significantly reduce the tumor volume of colon cancer xenograft mice models likely through the suppression of the TLR4/NF-κB p65 axis." (PMID 34884547, 2021). "The activation of TLR4 can also induce apoptosis in multiple cancer types, such as leukemia, liver cancer, and colon cancer." (PMID 34141706, 2021). "In colon cancer studies, F. nucleatum stimulation of proinflammatory cytokines was found to occur by both TLR4-dependent and -independent mechanisms." (PMID 33653893, 2021). "TLR4 expression in the colonic tumor microenvironment has been found to be positively correlated with the disease progression of CRC." (PMID 34479599, 2021). "Peptostreptococcus has been shown to induce TLR2 and TLR4 expression in colon cancer cells in culture, thus boosting levels of reactive oxygen species and cell proliferation." (PMID 33441939, 2021). "For example, RETN, as a pro-inflammatory cytokine, was found to bind to TLR4 on the cell membrane of colon cancer, initiating Toll-like receptor 4-myeloid differentiation primary response gene 88-dependent activation of ERK." (PMID 34158059, 2021). "The gene expression of TLR4 was revealed to be increased in classic mouse models of acute and chronic colitis induced by DSS, and the highest level of TLR4 expression was seen in colonic tumors induced by AOM/DSS." (PMID 34479599, 2021). "Resistin binds to Toll-like receptor 4 (TLR4) on the colon cancer cell membrane and initiates TLR4-myeloid differentiation primary response 88 (MYD88)-dependent activation of ERK." (PMID 33167521, 2020). "It was reported that TLR4 was involved in facilitating migration of colon cancer cells and preserving them from immune surveillance and cell death." (PMID 32158615, 2020). "In mouse models of colon cancer, stimulation of TLR4 leads to the overexpression of an ICOS ligand (B7-H2) and programmed cell death ligand 1 (B7-H1) as well as downregulation of death receptor Fas; these changes prolong tumor survival." (PMID 32012718, 2020).
colon carcinoma (continued). "Aspirin (the most commonly used anti-inflammatory agent) can inhibit TLR4 expression in C26 colon cancer cells." (PMID 32849545, 2020). "F. nucleatum also induces resistance to chemotherapy in colon cancer via TLR4/NF-κB pathway-induced autophagy." (PMID 32850497, 2020). "The highly effective anti-cancer activity of MD2 blockade strategies was likely attributed, at least in part, to this upregulated MD2 and TLR4 in colon cancer." (PMID 32210720, 2020). "Quercetin inhibited the migration and invasion of the human colon cancer Caco-2 cell line via regulation of the toll-like receptor 4 (TLR4)/NF-kB pathway." (PMID 32059369, 2020). "For instance, researchers have suggested that the TLR4 pathway accelerates colon cancer cell migration and protects cancer cells against apoptosis and immune surveillance." (PMID 32095158, 2020). "Recent studies have demonstrated that TLR4 expression and signaling induce an upregulation of IL-6 in different context such as colon cancer, Fragile X, and human bladder epithelial cells." (PMID 32230799, 2020). "The functions of TLR4 in the migration of the colon cancer cell line were analyzed by infecting cells with lentivirus containing TLR4 siRNA." (PMID 29308184, 2018). "Consistent with our data, in colon cancer, NF-κB can be induced by LPS binding to TLR4, further indicating the essential role of TLR4/NF-κB pathway in cancer development." (PMID 29788922, 2018). "RT-PCR and western blotting were used to explore Toll-like receptor 4 (TLR4) expression in colon cancer cell lines." (PMID 29308184, 2018). "The TLR4 antagonist was reported to facilitate tumor reduction via enhancing apoptosis in colon cancer." (PMID 29560134, 2018). "TLR4 is also overexpressed in melanoma, colon cancer, and breast cancer, and the expression of its downstream adaptor protein MyD88 is elevated in melanoma and colon cancer." (PMID 29636841, 2018). "Our data suggest that aspirin as a potential inhibitor for LPS-induced EMT and metastasis of colon cancer cells by decreasing the expression of TLR4 and NF-κB signaling." (PMID 29308184, 2018). "TLR4 signaling is reported to be related to numerous cancers, such as lung, liver, gastric, pancreatic, ovarian, and colon cancer, all the cancers above are generally believed to have some sort of link with local chronic inflammation." (PMID 29560134, 2018). "The results reported by the authors demonstrate that lipopolysaccharide (LPS) induced the metastasis and epithelial-mesenchymal transition (EMT) phenotype of colon cancer cells via a toll-like receptor 4 (TLR4) dependent manner." (PMID 29942487, 2018). "Recently, TLR4 was reported to be highly expressed in cancers, including colon cancer, pancreatic ductal adenocarcinoma, oral squamous cell carcinoma, ovarian epithelial cancer, non-small lung cancer and hepatocyte carcinoma." (PMID 29560134, 2018). "We found that the enhancement of LPS on the migration of colon cancer cells by inducing epithelial-mesenchymal transition (EMT) phenotype demonstrated a TLR4-dependent manner." (PMID 29308184, 2018). "We have previously reported on associations of TLR2 and TLR4 SNPs with colon cancer risk and survival and identified significant GEI of alcohol and TLR2 gene with colon cancer risk." (PMID 28956832, 2017). "Gene expression microarray analysis showed activation of the TLR4/MYD88/NF-κB pathway in colon cancer cells upon infection with F. nucleatum, and in vitro experiments confirmed that F. nucleatum regulates miRNA 21 expression via the TLR4/MYD88/NF-κB pathway." (PMID 28632155, 2017). "In the same context, several studies reported an increase in the TLR4 expression in colon cancer cell lines (HT29, SW480, and KM20)." (PMID 28408791, 2017). "TLR4 is overexpressed in colon tumors resulting from chronic ulcerative colitis in humans and from inflammation in animals." (PMID 29228570, 2017).
colon carcinoma (continued). "The high level of TLR4 expression in colon cancer tissues is mainly due to infections by bacteria in the human colon and leads to induction of an acute secretion of inflammatory cytokines mediated by NF-κB." (PMID 26771524, 2016). "The higher level in TLR4 expression in colon cancer tissues compared to normal tissues is mainly due to infections by bacteria in the human colon, explaining a potential origin of colon cancer." (PMID 26771524, 2016). "The current study aims to evaluate the expression of TLR4 in CRC and to examine the potential implication of four SNPs of human TLR4 (rs32770150, rs310759931, rs10759932and rs4986790) with the risk of colon cancer in the Saudi Arabia population." (PMID 26771524, 2016). "Further analysis of the TLR4 genotype distribution after correlation with age revealed that the median age of onset of present colon cancer samples is 56 years and in control groups is 52 years." (PMID 26771524, 2016). "TLR4 has been detected in cell lines of many human cancers, including gastric, breast, lung, prostate and colon cancer." (PMID 27409669, 2016). "Protein expression generally did not correspond to mRNA expression for the remaining markers, i.e. GRM8, LY6G6D/F, SLCO1B3 and TLR4, indicating that protein levels for these markers are likely regulated after translation in this set of colon cancer cells." (PMID 26894861, 2016). "TLR4 was highly expressed (p <0.001) in colon cancer tissues compared to normal colon tissues (2.53 ± 0.32) and (1.01 ± 0.01) respectively." (PMID 26771524, 2016). "Here we show enhanced expression of TLR-4 on colon cancer tissues and its role in the inflammatory pathways particularly via NF-κB pathway, a fundamental molecular hub linking inflammation and cancer." (PMID 26771524, 2016). "Our results show that TLR4 is over-expressed in colon cancer tumor epithelial cells, which constitute the first line of defense against foreign agents." (PMID 26771524, 2016). "TLR4/MyD88 signaling in myeloid cells has been shown to support spontaneous colon cancer development." (PMID 27679575, 2016). "Reverse-transcription polymerase chain reaction was performed for detection of TLR2 and TLR4 mRNA in colon cancer and normal colon epithelial cells using commercially available primers." (PMID 24390484, 2014). "Up to 47% of sporadic colon cancers express TLR4 protein with meaningful impact on survival and other clinical indices." (PMID 24887394, 2014). "The data demonstrate that TLR4 expression is at least doubled in adenomas and colon cancers compared with normal tissue." (PMID 24887394, 2014). "IHC staining confirmed the positive relationship between TLR4 staining score in the CRC tumor stroma and epithelium with tumor stage, with up to 47% of colon cancer stroma positive for TLR4 staining." (PMID 24887394, 2014). "Increased expression of TLR4 in colon cancer (stroma) significantly accelerates the development of the disease and is a poor prognostic factor." (PMID 24390484, 2014). "This increased proliferation in intestinal epithelial cells (IEC) resulted in significantly longer colonic crypts in the villin-TLR4 mice than in wild-type mice especially in the distal colon, the site of most colon cancers in humans." (PMID 23691015, 2013). "The purpose of this study was to investigate the impact of Asp299Gly and Thr399Ile TLR4 polymorphisms on Chemosensitivity of HCT-116, Colon Cancer Cells to 5-Fluorouracil." (PMID 24250621, 2013). "We show that a subset of adenomas–a precursor of colon cancer, and sporadic CRCs have increased epithelial expression of TLR4." (PMID 23691015, 2013). "As a conclusion, TLR4 expression can contribute to the chemosensitivity of colon cancer cells to 5-FU treatment." (PMID 24250621, 2013). "We found that villin-TLR4 mice showed an increased number of colonic tumors compared to WT mice as well as increased β-catenin activation in non-dysplastic areas." (PMID 23691015, 2013).